MAOB (monoamine oxidase B)
Diseases named in the same sentence as MAOB in open-access papers (continued):
Sharing a sentence is not in itself a finding about the gene and the disease.
tumor (continued). "While the contrasting roles of MAOA and MAOB in PCa progression remain unexplained, we speculated that distinct substrates may modulate the tumour‐suppressive activities of MAOB and oncoprotein activities of MAOA." (PMID 38520217, 2024). "However, within the amine oxidase family, MAOA and MAOB staining demonstrated evidence of intratumoral heterogeneity, with expression observed in only certain parts of the tumor area in minor cases." (PMID 37509535, 2023). "Subsequently, we analyzed 32 paired tumor-normal tissue samples for NE synthase and degrading enzyme mRNA expression in TCGA database, and the MAOA (p ≤ 0.001) and MAOB (p ≤ 0.001) mRNA levels showed significantly higher expression in normal tissues than in the paired tumor tissues." (PMID 33855088, 2021). "Likewise, our study demonstrated a significant downregulation of MAOB in tumor tissues when compared with their adjacent non-tumor tissues." (PMID 34209963, 2021). "Finally, tumours with high grade (III-IV) are characterized by MAOB gene overexpression and CKMT2 gene downregulation, both related to arginine and proline metabolism pathway." (PMID 31949199, 2020). "An alteration in the levels of Sp1 and Sp3 could link MAOB and HiF-1α levels to tumor grade and aggressiveness." (PMID 26689994, 2016). "Elevated norepinephrine is related to activated glycolysis, so the levels of MAOA and MAOB in tumor tissues are closely related to the prognosis of patients with PD-1 and other immunotherapy.However, these conclusions were based on the finding that tumor cells consume high levels of glucose." (PMID 36387147, 2022). "NAB2, CYP27A1, NPIPB4, MAOB, and SIAE, demonstrated lower expression for the OSCC group compared with a non-tumor group." (PMID 40723410, 2025). "The mean H-scores of ACN in the tumor cells were MAOA 180.6, LOX 163.3, AOC3 46, and MAOB 24.4, and in stromal cells, they were LOX 142.1, MAOA 126.6, AOC3 26.7, and MAOB 3.1." (PMID 37509535, 2023). "Data showed significantly increased MAOB expression (Z score = 4.01) and slightly decreased MAOA expression (Z score = −1.18) in CRC tumor tissues." (PMID 32316576, 2020). "We observed an average overexpression of ~37 folds for MAOB and ~eight folds for FABP7 in grade III tumours compared to grade I, whilst RBP1 average grade III expression was analogous to that of grade I." (PMID 33167358, 2020). "Except for MAOB and ALDH2, the expression levels of other metabolism-related genes in LUAD was all in the tumor tissues." (PMID 33193873, 2020). "MAOB, NPIPB4, CYP27A1, and SIAE showed significantly lower expression levels in OSCC tumor tissues compared to normal tissues." (PMID 31963366, 2020). "Expression of MAOB in LGG and GBM is highly elevated, and its levels correlate with the degree of tumor hypoxia." (PMID 29844863, 2018). "Furthermore, acetate produced by glucose metabolism in tumor cells is secreted into the TME, upregulating the expression of monoamine oxidase B (MAO-B) and MCT1, which stimulates reactive astrocyte proliferation." (PMID 41355959, 2026). "Collectively, these clinical findings suggested that MAOB is a valuable prognostic marker in RCC, especially ccRCC, and may play a crucial role in regulating tumor growth." (PMID 41338163, 2025). "Among these, monoamine oxidase B (MAOB) has emerged as a noteworthy player due to its involvement in the endogenous synthesis of geranylgeranoic acid (GGA), a lipid mediator with potential tumor-suppressive properties." (PMID 41142201, 2025). "However, only the drug metabolism by cytochrome P450 pathway was significantly enriched (fold enrichment = 13.4, FDR = 0.007) and all the five genes that fall within this pathway (FMO3, FMO2, FMO4, MAOB, CYP3A5) are upregulated in NS tumor tissue." (PMID 38978078, 2024). "Patients with lower expression level of MAOB corresponded to a better prognosis, and even in tumor microenvironment, cells expressing MAOB were mainly enriched in non-tumor cells." (PMID 38434969, 2024).
tumor (continued). "Other bioinformatic analyses also revealed a negative correlation between STC2 and MAOB expression in human tumours." (PMID 38464261, 2024). "Because MAOA and MAOB functioned in dopamine degradation, we hypothesized that elevated HIF-1A might decrease the dopamine in MES-like high tumor." (PMID 36720864, 2023). "Notably, the expression levels of both MAOB and LRP1 were downregulated in tumor samples compared with normal samples in the TCGA and GEO databases, but the expression of FASN was upregulated." (PMID 34819038, 2021). "Meanwhile, MAOA and MAOB were detected to be downregulated, meaning that the additional tumor derived dopamine would not be degenerated in time." (PMID 33898321, 2021). "Interestingly, the mRNA levels of MAOB, NABNPIPB4, CYP27A1, and SIAE were lower in OSCC tumor tissues as compared to normal tissues, which is consistent with our results in the saliva samples." (PMID 31963366, 2020). "Additionally, Chi-squared and Wilcoxon rank sum tests in TCGA-KIRC cohort demonstrated a negative correlation between MAOB expression and tumor sizes." (PMID 41338163, 2025). "Accordingly, the age-associated downregulation of MAOB, and the resultant loss of hepatic GGA, may represent not only a metabolic alteration but also a disruption of the liver’s intrinsic tumor surveillance system." (PMID 41142201, 2025). "The discussion focuses on the metabolic changes that occur with aging, its consequences for GGA availability, and the compensatory role of cytochrome P450 3A4 (CYP3A4), a hepatic enzyme that may partially substitute for MAOB in GGA synthesis but also potentially promotes tumor progression." (PMID 41142201, 2025). "Moreover, a negative correlation between STC2 and MAOB levels is also identified in human tumour samples." (PMID 38464261, 2024). "Our data showed that tumor tissues had significantly lower MAOA expression (p < 0.0001) and higher MAOB expression (p = 0.0002) compared to the paired non-tumor counterparts." (PMID 32316576, 2020).
cancer (42 papers, 2008 to 2026). A tumor composed of atypical neoplastic, often pleomorphic cells that invade other tissues. "The ICBatlas analysis revealed the conserved bidirectional pattern (protective MAOB/SERPINA1 vs. risk-enhancing IGFBP2/LGR6) of the four-gene signature as a pan-cancer theoretical framework for risk stratification." (PMID 40821817, 2025). "The Spearman correlation coefficient (ρ) was 0.822 between the mRNAs of MAOA and MAOB in the same cancer tissues, indicating a significant positive association (p < 0.001)." (PMID 34209963, 2021). "MAOB was related to cancer immune infiltration and linked to the prognosis of LUAD." (PMID 37189138, 2023). "Moreover, increased expression of MAOB mRNA was significantly associated with COMT mRNA in the same cancer tissues (ρ = 0.738; p < 0.001), and increased expression of MAOA mRNA was significantly associated with COMT mRNA in the same cancer tissues (ρ = 0.557; p < 0.001)." (PMID 34209963, 2021). "Additional contributors such as MAOB and ACADVL have known associations with oxidative signaling and cancer metabolism." (PMID 40941703, 2025). "To further investigate the immune associations of the three hub genes (PYGM, MAOB, TIMP1), we performed immune cell infiltration analyses across 33 TCGA cancer types using ssGSEA and CIBERSORT algorithms." (PMID 40873584, 2025). "The involvement of MAOB in this pathway positions the enzyme as a critical metabolic node linking lipid metabolism to cancer prevention." (PMID 41142201, 2025). "In HOK, DOK, OECM-1, and HSC-3 cancer cells, compared to the control group, downregulation of MAOB mRNA and protein was found to be statistically significant after arecoline treatment." (PMID 34209963, 2021). "Significantly strong positive associations were also found between the mRNAs of MAOA, MAOB, and COMT in the same cancer tissues." (PMID 34209963, 2021). "Recently, several studies have discussed the expression levels of monoamine oxidase (MOA) A (MAOA) and MAOB in cancers; however, controversial characteristics were identified for these two enzymes." (PMID 32316576, 2020). "The current findings support previous suggestions that MAOB can be exploited for the killing of cancer cells." (PMID 26689994, 2016). "5-Aza treatment also upregulated MAOB expression in SAS HNSCC cells, indicating that methylation blockade may be a potential strategy for inducing MAOB in several cancers." (PMID 41338163, 2025). "Relationships of MAOB SNPs with cancer have been infrequently discussed." (PMID 38520217, 2024). "However, for monoamine oxidase B (MAOB), cancers in advanced stages (stages II, III, and IV) presented higher expression levels of MAOB than those in stage I." (PMID 32316576, 2020). "Monoamine oxidases A and B (MAOA and MAOB) are highly expressed in many cancers." (PMID 26689994, 2016). "Thus, MAOB upregulation potentially drives cells metabolically closer to cancer cells." (PMID 32316576, 2020). "This review examines the age-dependent regulation of hepatic GGA levels via MAOB and CYP3A4 pathways and assesses its relevance to age-related cancer biology." (PMID 41142201, 2025). "Beyond their potential roles in liver tumor biology, both MAOB and CYP3A4 are well-characterized enzymes with established physiological functions in non-cancer contexts." (PMID 41142201, 2025). "Ligands activated RARα/Sp1-induced monoamine oxidase B (MAO-B), CADM1, E-cadherin and the folate receptor-β gene (FRβ) in cancer cells." (PMID 39858066, 2025). "Monoamine oxidase B (MAOB), a neurotransmitter‐degrading enzyme, was reported to reveal conflicting roles in various cancers." (PMID 38520217, 2024). "The monoamine oxidase B (MAOB) and hypoxia upregulated 1 (HYOU1) have been reported to be upregulated in hepatotoxicity as well as in various cancers." (PMID 38992651, 2024).
cancer (continued). "Consistent with the TCGA and GEO results, we also found that the expression levels of MAOB and LRP1 were downregulated in cancer tissues compared with paracarcinoma tissues, and the expression of FASN was upregulated." (PMID 34819038, 2021). "Namely, the expression levels of MAOB and LRP1 were downregulated in cancer tissues compared with paracarcinoma tissues, and the expression of FASN was upregulated." (PMID 34819038, 2021). "To evaluate the pan-cancer robustness of our 4-gene signature (MAOB, IGFBP2, SERPINA1 and LGR6), we leveraged the ICBatlas database—comprising 93,000+ patients across 18 cancer types (including 12 cancers with multi-omics profiling) and 30 immune checkpoint inhibitor (ICI) treatment cohorts." (PMID 40821817, 2025). "Moreover, quantitative real-time PCR suggested that the expression levels of MAOB and LRP1 were downregulated in cancer tissues compared with paracarcinoma tissues, and the expression of FASN was upregulated." (PMID 34819038, 2021). "We are currently investigating a number of MAOB sensitive pro-drugs, such as MP-MUS, that may be useful in the treatment of cancers that overexpress MAOB." (PMID 26689994, 2016). "However, whether MAOB can induce oxidative stress and promote the EMT in cancers such as CRC is still unclear." (PMID 32316576, 2020).
neurological disorders (27 papers, 2011 to 2026). "MAOB has been linked to the activity of platelets and dysfunction of nitric oxide synthase pathway observed in number of neurological diseases (recently reviewed in Leiter and Walker17)." (PMID 34017039, 2021). "One of the most common approaches to treating neurological disorders is the inhibition of monoamine oxidase B (MAO-B)." (PMID 39769961, 2024). "The inhibition of monoamine oxidase B (MAO-B) could be an effective approach for the treatment of various neurological disorders." (PMID 32705910, 2020). "Comparative molecular docking and dynamics simulations suggest that the inhibition of MAOB activity by 2,7-BCZ is a potential initiating event in PHCZ-induced neurological disorders." (PMID 41725537, 2026). "The PET radioligand [11C]L-deprenyl-D2 binds to monoamine oxidase B (MAO-B), enabling studies of neuroinflammation in various neurological disorders." (PMID 41546435, 2026).
brain diseases (6 papers, 2013 to 2025). "MaoB, which is known to relate to apoptotic cell death in brain diseases, and DNase I, which is involved in necrotic cell death, were specifically increased following oral Shigella infection." (PMID 24260541, 2013). "Monoamine oxidase B (MAO-B) plays a prominent role in the degradation of monoamine neurotransmitters, and abnormally high levels of MAO-B activity are associated with various brain diseases." (PMID 38932754, 2024).
infection (3 papers, 2016 to 2022). The state of being infected such as from the introduction of a foreign agent such as serum, vaccine, antigenic substance or organism. "A moderate increase in MAOB expression at 24 h post-infection, followed by a substantial increase (up to 2.5-fold) at 48 h post-infection was detected." (PMID 36611805, 2022). "The expression of mRNAs for Cadherin, Albumin, GstA4 and AFP were significantly increased 20 and 40 days after the first infection and those for MaoA and MaoB were augmented to some extent." (PMID 28352551, 2016). "Higher mRNA levels of MAOA, MAOB and VMAT2 were observed upon infection in these cells also, while DBH and COMT expression was not significantly altered." (PMID 36611805, 2022).
central nervous diseases (1 paper, 2021). "The positron emission tomography (PET) radioligand 18F-THK5351 is now used to evaluate monoamine oxidase B expression in the reactive astrogliosis seen in various central nervous diseases." (PMID 34939155, 2021).
MAOB also shares sentences with these, for which no sentence is quoted: Parkinson (53 papers); dementia (20); amyotrophic lateral sclerosis (8); neuroblastoma (8); progressive supranuclear palsy (7); Stroke (7); diabetes (6); movement disorder (6); alcohol use disorder (5); heart failure (4); post-traumatic stress disorder (4); restless leg syndrome (4); sleep disorder (4); Arthritis (3); ischemic stroke (3); panic disorder (3); personality disorder (3); social phobia (3); amyloid (2); behavioral disorders (2); bladder cancer (2); Bradykinesia (2); brain ischemia (2); brain tumor (2); cardiac diseases (2); corticobasal degeneration (2); corticobasal syndrome (2); Delusion (2); endotoxemia (2); hearing loss (2).
A further 100 diseases each share a sentence with MAOB in 2 papers or fewer.